CD68 (CD68 molecule)
Diseases named in the same sentence as CD68 in open-access papers (continued):
Sharing a sentence is not in itself a finding about the gene and the disease.
osteoarthritis (11 papers, 2013 to 2025). A noninflammatory degenerative joint disease occurring chiefly in older persons, characterized by degeneration of the articular cartilage, hypertrophy of bone at the margins and changes in the synovial membrane. "The results showed increased numbers of WNT5A+ and CD68+ expressing osteoclasts in the joints of the PsA patients compared to those of the osteoarthritis patients (p < 0.01)." (PMID 35055107, 2022). "Additionally, chronic macrophage presence (CD68+) interferes with regeneration, reinforcing the inflammatory component in osteoarthritis and osteonecrosis." (PMID 40869671, 2025). "Evaluation of the expression of CD68+ cells in the synovial tissue of patients with PsA proved their significantly stronger representation in the synovial tissue of inflammatory joint disease compared to degenerative joint disease." (PMID 39629578, 2024). "The GM-CSF receptor was reported to be overexpressed in CD68+ and CD163+ macrophages from the ST of RA and PsA patients compared with osteoarthritis patients and healthy controls." (PMID 33679701, 2020). "Serial synovial tissue sections from all RA patients, 13 osteoarthritis, and 10 orthopedic arthropathies patients were stained with hematoxylin and eosin and immunohistochemically for MMP-3, CD3, CD20, CD38, CD68, and CD15." (PMID 25147433, 2014). "ZEB1 was also expressed in CD68+ macrophages in the synovial membrane of PsA patients but it was nearly absent in the synovium of osteoarthritis patients." (PMID 37978290, 2023). "In situ hybridization showed expression of C15orf48 mRNA almost exclusively in CD68+ macrophages of RA biopsies, whereas no expression was detected in synovial biopsies of patients with osteoarthritis (OA)." (PMID 34878835, 2021). "Therefore, we investigated the difference of CD68+WNT5A+ osteoclasts in the destructive joints of PsA and non-inflammatory arthritis (osteoarthritis)." (PMID 35055107, 2022).
tauopathy (11 papers, 2019 to 2026). Neurodegenerative disorders involving deposition of abnormal tau protein isoforms (tau proteins) in neurons and glial cells in the brain. "As expected, microvessel length was negatively associated with the level of tauopathy marker (r = −0.56, p < 0.0001), with CD68+/Iba1+ microglia (r = −0.47, p = 0.0001) and with CD3+/CD8+ T lymphocytes (r = −0.48, p < 0.0001)." (PMID 34687487, 2021). "While many studies have used Iba1 and CD68 to mark microglial cells, these markers are also expressed in monocyte-derived macrophages, which have functional roles in tauopathies." (PMID 40862760, 2025). "Perhaps consistent with this, tauopathy cases in our series showed the highest anti-CD68 reactivity scores although here too group sizes were underpowered to allow definitive conclusions." (PMID 38698465, 2024). "In contrast to CD31, pCD31 level was positively correlated with the tauopathy marker (r = +0.40, p = 0.002), with the CD68+/Iba1+ microglia (r = +0.45, p = 0.0003) and with CD3+/CD8+ T lymphocytes (r = +0.54, p < 0.001; bottom row)." (PMID 34687487, 2021). "CD31 expression level was negatively correlated with the tauopathy marker (r = −0.48, p < 0.0001), with the CD68+/Iba1+ microglia numbers (r = −0.35, p = 0.007) and with CD3+/CD8+ T lymphocytes (r = −0.28, p = 0.03; middle row)." (PMID 34687487, 2021). "Concordantly, CST reduced expression of CD68, GFAP, IL-6, TNF-α, CXCL1, and CXCL10, extending its known peripheral anti-inflammatory actions 20,38 to the central nervous system and establishing CST as a regulator of neuroimmune homeostasis in Tauopathy." (PMID 41509358, 2026). "mCRP‐CD31 binding was positively correlated with the tauopathy marker (r = +0.45, p = 0.02), with the CD68+/Iba1+ microglia numbers (r = +0.52, p = 0.02), but not with CD3+/CD8+ T lymphocytes in the brain (top row)." (PMID 34687487, 2021).
thyroid cancer (11 papers, 2013 to 2025). "Tumor-associated macrophages (TAMs), including both M1 (CD68+) and M2-type (CD163+), were shown to be the most numerous immune cells infiltrating thyroid carcinoma." (PMID 39936166, 2025). "For instance, CD68+ TAMs were identified as predictors of favourable prognosis in gastric, colon and prostate adenocarcinomas, but as a predictor of poor prognosis in neuroblastoma, thyroid cancer and non-functioning pancreatic neuroendocrine tumours." (PMID 31875303, 2020).
vasculitis (11 papers, 2012 to 2025). "Studies conducted on cases of vasculitis have demonstrated the multinucleated giant cells and other CD68 positive macrophages as sources of vascular endothelial growth factor (VEGF) and interferon gamma, both of which are mediators of angiogenesis." (PMID 33722245, 2021). "The diagnosis of the conjunctival biopsy showed severe subacute inflammation with aggregates of CD68+ macrophages (granulomatous formation) and vasculitis, findings consistent with granulomatosis with polyangiitis." (PMID 25632308, 2015). "The only CD68-positive macrophages observed were apparently in the process of scavenging medial and adventitial debris resulting from SA/C vasculitis." (PMID 22723916, 2012). "Because high‐dose corticosteroids followed by serial immunotherapies, including IVIg, rituximab, and tocilizumab, were ineffective, a brain biopsy was performed, revealing chronic granulomatous and suppurative vasculitis with diffuse infiltration of CD68‐positive macrophages." (PMID 35040583, 2022). "Histopathological sections of the vitreous, aspirated from patients with vasculitis that developed after brolucizumab injection, revealed infiltration of CD20 positive B cells, CD3, 4, and 8 positive T cells and CD68 positive histiocytes." (PMID 34871313, 2021). "Cytoplasmic positivity for MMP2 was occasionally observed in mild cases of ACR and AMR, but without significant associations with vasculitis, the Quilty effect, or inflammatory marker expression (CD4, CD8, and CD68)." (PMID 41009699, 2025). "Pathological examination revealed the presence of CD68+ macrophages and CD8+ lymphocytes but no signs of demyelination, axonal loss, or vasculitis." (PMID 39055723, 2024).
xanthoma (11 papers, 2009 to 2025). A non-neoplastic disorder characterized by a localized collection of histiocytes containing lipid. "Histopathologic examination showed xanthogranulomatous inflammation, consisting of sheets of cluster of differentiation 68 (CD68)-positive, foamy, lipid-laden histiocytes (xanthoma cells) surrounding areas of necrosis with pseudocyst formation." (PMID 41426915, 2025). "These xanthoma cells contain plenty of lipids, and CD68, CD163, and CD63 are positive in immunohistochemistry, indicating a macrophage phenotype." (PMID 40502883, 2025). "Histologically, xanthoma histiocytes are foamy macrophages containing intracellular lipid droplets, typically observed within the lamina propria, that stain positive with CD68." (PMID 39006590, 2024). "Immunohistochemically, xanthomas demonstrate strong cytoplasmic positivity for CD68, a marker used to identify the activated macrophages." (PMID 38502367, 2024). "Lipid-laden macrophages, the main cells found in xanthomas, are mainly distributed in the lamina propria and expressing CD68." (PMID 36936665, 2023). "Usually, the foamy cells in xanthomas show the marker CD68, a highly glycosylated, 110-kDa membrane protein that can be highlighted with monoclonal KP1 or PGM1 antibodies, yet has a weak cytoplasmic positivity with periodic acid–Schiff (PAS) staining." (PMID 32149048, 2020). "On immunohistochemical staining, there was a neutrophilic infiltrate of the epidermis with CD68 positive xanthoma cells restricted to the papillary dermis, mixed with other chronic inflammatory cells." (PMID 24396610, 2013). "Although both NOF and BFH exhibit variable positivity to CD68, they are strongly positive for factor XIIIa + making this immunohistochemical tool important in differentiating tumors with fibrohistiocytic lineage from xanthoma of bone." (PMID 38502367, 2024). "Besides CD68, supplementary markers such as S100, factor XIIIa + and CD1a are useful in separating xanthomas from other diseases." (PMID 38502367, 2024). "Histopathologic examination revealed foamy histiocytes positive for CD68 and negative for S100, consistent with a xanthoma." (PMID 40693216, 2025). "Histologically, xanthomas consist of aggregates of foamy histiocytes that are strongly positive for CD68 and negative for S100 protein, as seen in our case." (PMID 40693216, 2025). "All cases demonstrated strong positive cytoplasmic staining for CD68 in the granular xanthoma cells and negative for S100 staining." (PMID 38502367, 2024). "The xanthoma cells showed positive staining with CD68 in all patients while they were negative to S-100 and CD1a." (PMID 38504269, 2024). "Gastrointestinal xanthomas are composed of cells with abundant foamy cytoplasm containing lipid characteristically positive for CD68 with no mucin or pigment deposition." (PMID 26167322, 2015). "In popular xanthoma, histiocytes are CD68, KiM1p, and HAM 56 positive but negative for XVIIIa, S-100, lysozyme and CD56." (PMID 19814780, 2009).
hyperlipidemia (10 papers, 2011 to 2025). "CD68 is a macrophage marker; CD68-positive cells have been found in liver tissue damaged by hyperlipidemia." (PMID 35845925, 2022). "The marker CD68 identifies macrophages, and CD68-positive cells were found in liver tissue damaged by hyperlipidemia." (PMID 30526612, 2018). "Consistent with resolution of hyperlipidemia and reduction in liver triglyceride and cholesterol content, WT and CD68-Tg mice demonstrated lower percent fat mass relative to A2bAR KO mice." (PMID 24892847, 2014). "We found that western diet-fed apoE-/- mice treated with either atorvastatin or rosuvastatin led to a substantial reduction in the CD68+ cell content in the plaques despite continued hyperlipidemia." (PMID 22163030, 2011). "CD68-positive cells were found in liver tissue damaged by hyperlipidemia." (PMID 30049280, 2018).
Hypertension (10 papers, 2013 to 2024). The presence of chronic increased pressure in the systemic arterial system. "For example, CD68+ macrophages and CD4+ T cells were rich in mPVAT from obese mice during progression of hypertension, which was linked to impaired mPVAT-mediated vasodilation." (PMID 39156105, 2024). "In Ang II-induced hypertension, aPVAT contained abundant CD68+ macrophages and CD3+ T cells, as along with increased expression of RANTES and IFN- γ." (PMID 39156105, 2024). "To investigate the roles of macrophages in hypertension-induced cardiac dysfunction, we further clustered macrophages, which expressed CD68, Adgre1, Fcgr1 and Csf1r, into 15 small populations." (PMID 38443404, 2024). "IF assay was performed with the macrophage-specific marker CD68 in the aortas of hypertensive patients and healthy subjects, and the data proved that CD68+ macrophages were more abundant in hypertension than in normal conditions." (PMID 37718359, 2023). "In contrast, presence of CD68+ macrophages, representing innate immunity, was markedly increased by DS‐induced hypertension." (PMID 31368189, 2019). "Kidney injury molecule-1 (KIM-1), a marker of renal tubular injury, was elevated in individuals with both hypertension and hyperuricemia, correlating with increased numbers of CD4+ T cells and macrophages (CD68+)." (PMID 38425055, 2024). "Moreover, hypertension-induced changes in geometric (wall thickness) and mechanical (axial stiffness) metrics also correlated well with CD45+ and CD68+ cells for both WT and Agtr1b−/− mice." (PMID 39192727, 2024). "Moreover, the CD206/CD68 mRNA ratio was decreased in PIH women, suggesting that decreased numbers of M2 macrophages are present in the decidua of women who later develop pregnancy-induced hypertension." (PMID 25071761, 2014).
invasive breast carcinoma (10 papers, 2008 to 2025). A carcinoma that infiltrates the breast parenchyma. "Along this line, high infiltration by CD68(+)PCNA(+) macrophages is associated with decreased recurrence-free survival (RFS) in patients with invasive breast carcinoma who received neoadjuvant chemotherapy." (PMID 40243442, 2025). "Furthermore, earlier studies report that a high density of CD68+ TAMs infiltration in invasive breast cancer was associated with higher vascularity and nodal metastasis, as well as reduced RFS and OS." (PMID 32607685, 2020). "This study aimed to compare CD163 expression with the widely used CD68 pan-macrophage marker in invasive breast carcinoma." (PMID 32372332, 2020). "Immunohistochemistry revealed that ObR, CD68, and IL-8 were significantly higher in invasive breast carcinoma tissue specimens than in benign and carcinoma in situ tissue specimens (P < 0.05)." (PMID 27588409, 2016). "Association of CD169+, CD68+, and CD8+expressing cells with clinicopathological parameters in the invasive breast cancer cohort." (PMID 27861544, 2016). "Moreover, there are no standardized methods for macrophage detection and different studies have used different markers (e.g., CD68, CD163, or CD206) and staining platforms to make conclusions about the prognostic value of macrophages in invasive breast cancer." (PMID 38720366, 2024). "The authors employed multiplex immunostaining, including CD20(+) B, CD3(+)CD8(+) T, CD3(+)FOXP3(+) regulatory T cells, CD68(+) cells, and CD8(+)Ki67(+) proliferating T cells, and found that the assessment of these markers in the TME was not a predictor of invasive breast carcinoma development." (PMID 40243442, 2025).
renal cell carcinoma (10 papers, 2013 to 2024). "PAX8 immunostaining and CD68 (PG-M1) negativity support the diagnosis of TFEB-rearranged renal cell carcinoma, whereas pure epithelioid PEComa/epithelioid angiomyolipoma has the opposite immunoreactivity, being negative for PAX8 and positive for CD68 (PG-M1)." (PMID 34069976, 2021). "None of the MiT family translocation renal cell carcinomas considered expressed CD68 (PG-M1) neither CK20." (PMID 35980471, 2022). "In these challenging cases, PAX8 (positive in TFE3-rearranged renal cell carcinoma and negative in pure epithelioid PEComa) and CD68 (PG-M1) (negative in TFE3-rearranged renal cell carcinoma and positive in pure epithelioid PEComa) are useful markers to reach the proper diagnosis." (PMID 39410016, 2024). "PAX8 and CD68 (PG-M1) are useful in differentiating them: CD68 (PG-M1) is reportedly positive and PAX8 negative in renal epithelioid-AMLs, whereas MiT family renal cell carcinoma is negative for CD68 (PG-M1) and positive for PAX8." (PMID 36740682, 2023). "Patients with renal cell carcinoma treated with neoadjuvant bevacizumab demonstrated reduced CD31+ MVD and a reduced number of total CD68+, but not CD163+ TAMs in comparison with untreated patients." (PMID 34209679, 2021). "Compared to renal cell carcinomas, renal EAML tumors are distinctively negative for cytokeratin and other epithelial markers, and positive for PMA, CD68 and calponin." (PMID 23628229, 2013).
triple-negative breast carcinoma (10 papers, 2018 to 2025). An invasive breast carcinoma which is negative for expression of estrogen receptor (ER), progesterone receptor (PR), and human epidermal growth factor receptor 2 (HER2). "We performed IHC analysis of ID4 protein and macrophage marker CD68 in a triple-negative breast cancer series." (PMID 29921315, 2018). "In another study, high TILs (CD3+, CD15+ and CD68+) were significantly correlated with low NLR and high LMR in locally advanced triple-negative breast cancer." (PMID 35336759, 2022). "Multiplex immunofluorescence (m-IF) analysis of human triple-negative breast cancer (TNBC) tissues demonstrated co-localization of MARCO with CD11b+ CD14+ cells that were negative for CD68 expression, suggesting potential expression of MARCO on M-MDSCs." (PMID 40695812, 2025).
depression (9 papers, 2021 to 2025). "Patients with symptoms of anxiety/depression had more CD68 + cells and higher M1/M2 ratios in the intestine mucosal layer compared to those without." (PMID 36906523, 2023). "In another study, spared nerve injury (SNI)-induced depression was associated with the activation of microglia through the upregulation of Iba1 and CD11b and increased levels of pro-inflammatory mediators (IL-1β, TNF-α, and CD68) in the PFC54." (PMID 36747075, 2023). "Furthermore, numerous studies have reported that the levels of CD68, an ideal marker of activated and phagocytic microglia, are elevated in depression models." (PMID 34489395, 2021). "In AD without depression and compared to controls, Iba1 and P2RY12 expression were reported unchanged, while CD68 and CD64 expression was increased." (PMID 39526037, 2024).
diabetic nephropathy (9 papers, 2014 to 2025). "It was found that inhibition of SGLT2 in human diabetic nephropathy patients had a positive effect on inflammatory response (via inhibition of CD68, p65, TLR4, MCP-1, and osteopontin)." (PMID 40143180, 2025). "In this cohort of diabetic nephropathy patients undergoing tissue biopsy, glomerular CD68+ cells predicted the development of ESRD even in advanced renal failure." (PMID 40338344, 2025). "The expression of FKN mRNA and protein in the renal tissue of diabetic nephropathy rats was significantly higher than that of the control group, and was positively correlated with the expression level of CD68." (PMID 38937701, 2024). "Infiltrating macrophages (F4/80+ and CD68+) were found in the glomeruli and renal tubules area in the diabetic nephropathy group compared with those in the normal control group." (PMID 35280997, 2022). "In biopsies of renal tissue with human diabetic nephropathy, with the progress of DN, CD68, M1 macrophages (iNOS), M2 macrophages (MR) and TREM-1 were mainly detected in interstitium and significantly increased compared with the control group." (PMID 31509552, 2019). "The number of CD68+ cells were significantly increased in the mice with diabetic nephropathy (DN+DMSO) when compared with controls (Control) (P<0.01)." (PMID 29425253, 2018). "Our results have shown TRAM34 significantly suppressed icreased CD68+ cells in the mice with diabetic nephropathy." (PMID 29425253, 2018). "Collectively, both CD68+ and F4/80+ macrophages, which are known to contribute to renal inflammation, were significantly suppressed in diabetic nephropathy kidneys by TRAM34 administration." (PMID 29425253, 2018). "Treatment with TRAM34 (DN+TRAM34) significantly reduced the increased CD68+ cells in mice with diabetic nephropathy (P<0.01)." (PMID 29425253, 2018). "Additionally, fewer M2 macrophages (CD68+/Arg-1+) were found in the tissues from patients with diabetic nephropathy." (PMID 35280997, 2022). "Paired immunohistochemistry for CD68 and MRP8 in serial sections suggested that MRP8 signals were, at least in part, observed in macrophages expressing CD68, as we reported in a mouse model of diabetic nephropathy." (PMID 24558454, 2014).